METTL14 (methyltransferase 14, N6-adenosine-methyltransferase non-catalytic subunit)
Diseases named in the same sentence as METTL14 in open-access papers (continued):
Sharing a sentence is not in itself a finding about the gene and the disease.
cancer (continued). "Some studies have shown that METTL14-mediated m6A modification is involved in regulating numerous genes in various types of cancer." (PMID 36936652, 2023). "Among the 68 HCC patient specimens that underwent immunohistochemical staining, all cancer tissues were positive for METTL14, YTHDF2, and ZC3H13 staining in contrast to the adjacent tissues." (PMID 36936652, 2023). "m6A modification has been reported in a number of studies on cancers, and METTL14 is one of the most important regulatory proteins." (PMID 36810285, 2023). "We specifically inquired the functional effect of METTL14 knockout by CRISPR‐Cas9 in various human cancer cell lines." (PMID 36794620, 2023). "Analyses of m6A regulators and TSs showed that TSs were positively correlated with METTL3, while inversely with METTL14 in most cancer types, although both were m6A methyltransferases adding methyl groups to mRNA." (PMID 36239411, 2023). "Suppression of ferroptosis, a novel iron-dependent form of cell death, was shown to be essential for cancer malignant behavior, and m6A regulators such as METTL14, FTO, YTHDF2 and YTHDC2 are involved in regulating ferroptosis." (PMID 37015927, 2023). "METTL3 and METTL14 participate in the maturation of primary (pri-)miRNAs such as miR-25-3p, pri-miR221/222, pri-miR-1246, pri-miR-375 and pri-miR-126 in different cancers." (PMID 37202385, 2023). "In PC, METTL14 knockdown enhanced sensibility of cancer cells to cisplatin, promoting apoptosis and autophagy by repressing AMPKα, ERK1/2 and mTOR signal pathways." (PMID 35974338, 2022). "Research shows that METTL3 is mainly expressed as an oncogene in digestive system cancer but that METTL14 plays a role in inhibiting cancer." (PMID 35484099, 2022). "The METTL14 knockdown group showed increased cancer metastasis and a higher metastatic ratio than the control group." (PMID 35036065, 2022). "Taken together, our results evidenced a new regulatory mechanism of Siah2 by METTL14-induced mRNA epigenetic modification and the potential role of Siah2 in cancer immunotherapy." (PMID 35154166, 2022). "Writers such as METTL3 and METTL14 show cancer-promoting or cancer-suppressive effects on the same or different cancer types." (PMID 35449086, 2022). "Altered expression levels of the proteins that regulate N6-methyladenosine (m6A) RNA methylation, including methyltransferase-like 14 (METTL14), are associated with cancer development." (PMID 35251990, 2022). "In this paper, we systematically summarize the latest research progress on METTL14 as a new biomarker for cancer diagnosis and its biological function in human tumors and discuss its potential clinical application." (PMID 35115038, 2022). "Two “writer” genes, METTL3 and METTL14, were shown to have opposing expression patterns in cancers compared to normal indicating that METTL3 and METTL14 functioned as a complex regulator in STAD." (PMID 36620557, 2022). "In contrast, the expression of METTL14 was upregulated in most cancer types, except BLCA, OV, and UCEC." (PMID 35794212, 2022). "Oncogenic functions for METTL14 have been suggested in several cancer types, including pancreatic, breast and AML." (PMID 36733939, 2022). "METTL14 regulates the initiation and progression of multiple cancers by acting as both oncogene and tumour suppressor gene; however, METTL14 can act as a promoter in some types of cancer." (PMID 36264762, 2022). "Although increased METTL14 expression has been shown to suppress the progression of certain types of cancer, it leads to increased proliferation of acute myeloid cells." (PMID 35251990, 2022). "Given the contradiction, the role of METTL14 in metastasis of cancers needs to be confirmed by further studies." (PMID 35804965, 2022).
cancer (continued). "METTL14 (methyltransferase-like 14) is a key methyltransferase of m6A and plays crucial roles in various cancers." (PMID 36288387, 2022). "Previous study has revealed that METTL14 exerts prohibitive function in cancers through m6A modification." (PMID 36288387, 2022). "In consistence with these observations, our results showed that enhanced METTL14 in cancer cell lines indeed activated Wnt/β‐catenin signalling pathway and elevated phosphorylated GSK3β." (PMID 36264762, 2022). "Sang J's team found that hsa-mir-146a-5p was regulated by the m6A “writer” METTL14 to function in cancer invasion and migration." (PMID 36093132, 2022). "Considering the important role of METTL14 in cancer progression, emerging studies have pay emphasis on the upstream regulatory mechanisms involved in the aberrant expression of METTL14 in cancer." (PMID 35974338, 2022). "Although many studies have shown an inhibitory effect on cancer, METTL14 has also been shown to stimulate the development and progression of tumors in some cases." (PMID 35115038, 2022). "Dysfunction of METTL14, the key catalytic protein forming the core m6A methyltransferase complex, has shown fundamental biological effects in cancer initiation and progression." (PMID 35650238, 2022). "The abnormal expression of METTL14 in cancers and other diseases is triggered by multiple mechanisms." (PMID 34904301, 2022). "Mentioned outcomes further confirmed that METTL14 plays as a cancer suppressor gene in STAD growth and metastasis in vivo." (PMID 34476213, 2021). "METTL14 plays a similar role in cancer as that of METTL3; it promotes DGCR8 to recognize and bind m6A-modified pri-miRNAs, which further mediates miRNA maturation." (PMID 34108450, 2021). "We observed that WTAP, METTL3 and METTL14 were significantly upregulated in cancer vs. normal tissues, with METTL3 showing the most significant deregulation." (PMID 34530916, 2021). "Surprisingly, even though METTL3 and METTL14 show different expression levels and functions in urological cancers, they both participate in cancer progression through cell growth- and cell death-related pathways." (PMID 35004679, 2021). "Further validation showed that METTL14 protein level was downregulated in representative CRC patient tissue compared with adjacent para-cancer tissue." (PMID 34916487, 2021). "METTL14 was down-regulated in all 11 cancer types while FTO and ALKBH5 were down-regulated in most cancer types except for KIRC." (PMID 33718187, 2021). "In summary, we identified a key regulatory METTL14‐miR‐99a‐5p‐TRIB2 feedback circuit that epigenetically represses p21 through Akt/mTOR/S6K1/HDAC2 to promote cancer stemness and radioresistance in ESCC." (PMID 34586732, 2021). "As a pivotal m6A methyltransferase, METTL14 has recently been reported to be crucial for cancer initiation and progression in hepatocellular carcinoma, bladder cancer and pancreatic cancer by regulating diverse targets." (PMID 34916487, 2021). "In HCC, the methyltransferase METTL14 seems to be a good prognostic factor for cancer metastasis and recurrence because of its role in promoting the maturation of miR-126 that inhibits the metastasis of HCC." (PMID 32443966, 2020). "Several studies have reported that METTL14 plays a complex role in the occurrence and development of malignant tumors." (PMID 33134390, 2020). "The catalytic protein methyltransferase-like 14 (METTL14) participates in mediate cellular N6-methyladenosine (m6A) deposition and is closely related to the occurrence and development of malignant tumors." (PMID 33134390, 2020). "Based on the existing results, METTL3 and METTL14 control cancer cell fate through cell growth- and cell death-related pathways." (PMID 32765970, 2020). "Methyltransferase-like enzyme 3 (METTL3) and methyltransferase-like enzyme 14 (METTL14) are two major enzymes involved in m6A modifications that play vital roles in various cancers." (PMID 32765970, 2020).
cancer (continued). "Low METTL14 expression in cancer cells leads to high P2RX6 expression via the ATP-P2RX6-Ca2+-p-ERK1/2(Extracellular Regulated protein Kinases 1/2)-MMP9 (Matrix Metallopeptidase 9) signaling pathway, which promotes renal tumor cell metastasis and invasion." (PMID 32765970, 2020). "METTL14 promotes proliferation of cancer cells by promoting the translation of oncogenes MYC and MYB through m6A modification in AML, and its absence promotes the myeloid differentiation." (PMID 33552994, 2020). "While in some other types of carcinoma, METTL14 exhibited the role of tumor suppressor by regulating m6A modification." (PMID 32710725, 2020). "It has been shown that silencing either METTL14 or ALKBH5 leads to cancer growth inhibition, a deregulation of the transforming growth factor– β signaling pathway, and epithelial-to-mesenchymal transition." (PMID 30654440, 2019). "Furthermore, targeting METTL14 may be a critical strategy for controlling EBV-associated cancers." (PMID 31226160, 2019). "METTL3 expression is increased in most cancers, while the dysregulation of METTL14 expression is cancer-dependent." (PMID 31847302, 2019). "Here, we will focus on therapeutic strategies and small molecules targeting the METTL3/METTL14 complex and discuss their potential applications in cancer treatment." (PMID 31024852, 2019). "METTL3 (methyltransferase-like 3)-catalyzed RNA methylation is required for cancer development, whereas the role of METTL14 varies with cancer types." (PMID 31735169, 2019). "Silencing of METTL14 decreases the m6A level in RNA transcripts and enhances cancer metastasis, both in vitro and in vivo, and downregulation of METTL14 in HCC serves as an adverse prognostic factor for recurrence-free survival." (PMID 29439529, 2018). "Overall, we propose that METTL14 could be involved in cancer progression by modulating the expression of these immune and inflammation‐associated genes." (PMID 41316520, 2025). "Targeting METTL3/METTL14 for degradation reduces m6A levels and inhibits cancer cell proliferation." (PMID 41446042, 2025). "Our discovery that PRMT1-catalyzed METTL14 arginine methylation plays a critical role in promoting ICL DNA repair gene expression reveals a new way of sensitizing cancer cells to ICL chemotherapy through targeting the METTL14 arginine methylation mediated m6A pathway." (PMID 41053315, 2025). "Specifically, METTL14 modulates IFN‐related genes (IFI27, IRS1, PSMA2, PSMA3), IL‐associated genes (CCL5, IL1B, IL32), and MHC class I genes (HLA‐A, B, C), implying a potential mechanistic link between METTL14 and cancer‐associated inflammatory responses." (PMID 41316520, 2025). "Previous work also showed that METTL14 could modulate cancer cell progression by targeting PI3K–Akt." (PMID 41345738, 2025). "Similarly, METTL14 also plays a role in cancer as METTL3, which also promotes the recognition and binding of DGCR8 to m6A-modified pri-miRNAs, thus facilitating miRNA maturation." (PMID 40734692, 2025). "In addition, METTL14 also plays an equally important role in inhibiting the progression of malignant tumors." (PMID 41256854, 2025). "All three N-terminal methyltransferases are frequently mutated in human cancers, which could suggest that METTL11B has its own important catalytic activity, or more similar to METTL14, is important for its regulatory role on METTL11A." (PMID 38429855, 2024). "METTL3 and METTL14 may thus be a potential prognosis marker and a therapeutic target in certain types of cancers." (PMID 39006762, 2024).
cancer (continued). "This suggests that the large differences in DNA binding sites observed in senescent or cancer cells may be due to partial dissociation of the METTL3-METTL14 complex or redundancy in the protein abundance of METTL3 compared to METTL14." (PMID 38965238, 2024). "This suggests that METTL14 might target genes involved in glycolysis to promote cancer cell growth and metastasis in LUAD." (PMID 39138186, 2024). "Our results demonstrated that LSD1 can upregulate YAP1 expression and promote stem-like properties in TNBC largely by repressing the transcription of METTL14, suggesting that the loss of METTL14 is another mechanism critical for the function of LSD1 in determining the aggressiveness of cancer cells." (PMID 39563370, 2024). "The diverse functions of METTL14 in these cancers may be attributed to tissue-specific expression or regulation." (PMID 39563370, 2024). "Accumulating evidence indicated that METTL14 played pivotal but distinct roles in various cancers." (PMID 39054337, 2024). "Because LSD1 and METTL14 regulate gene expression at different levels via crosstalk, METTL14 expression level may serve as an indicator for the efficacy of LSD1-based cancer therapy." (PMID 39563370, 2024). "In addition, as another important component of the m6A MTC, METTL14 also plays a role in malignant tumors." (PMID 39295872, 2024). "PiRNA-14633 augments METTL14 mRNA stability and protein expression in cancer cells." (PMID 38075202, 2024). "Disruption of METTL14-mediated M6A modification has been reported in various types of cancer 32-35." (PMID 38021156, 2023). "In addition to expression dysregulation, METTL14 can be directly recruited by LNC942 to promote cancer progression of BC." (PMID 36260366, 2023). "Most research studies on the m6A writer METTL3 or METTL14 indicate their oncogenic roles in cancer." (PMID 37612540, 2023). "METTL14 expression is dysregulated in cancers through different mechanisms." (PMID 36260366, 2023). "In previous studies, METTL14 has been regarded as a contributor to the oncogenesis of many cancers." (PMID 35804965, 2022). "RNA methylation (m6A modification) is mainly catalyzed by METTL3/METTL14 in human cancer cells." (PMID 35604883, 2022). "Importantly, special emphasis shall be given on the development of METTL14 inhibitors or activators in cancer treatment due to the double-edged sword roles of METT14 in gastrointestinal cancer." (PMID 35974338, 2022). "As for METTL14, most studies have identified its inhibitory effect on the metastasis of cancers." (PMID 35804965, 2022). "The immunohistochemistry (IHC) staining on tissue microarray also confirmed that METTL14 staining was decreased in CCA at the protein level and its downregulation displayed a significant association with poor cancer-specific survival in CCA (Log-Rank P = 0.045)." (PMID 35650238, 2022). "Combining the results of other studies and ours, we inferred that METTL14 plays a role in cancer suppression and could be a favorable index of cancer progression and prognosis." (PMID 36347025, 2022). "Importantly, METTL14‐KD led to significant m6A reduction and significantly inhibited migration and invasion traits of cancer cells." (PMID 35048498, 2022). "Finally, control over METTL3/METTL14 condensation is determined by its small molecule cofactor, S-adenosylmethionine (SAM), which regulates conformations of two gate loops, and some cancer-associated mutations near gate loops can impair METTL3 condensation." (PMID 35143475, 2022). "m6A modification involves a diversity of regulators, among which, methyltransferase-like proteins, METTL3 and METTL14, are believed to be the most important m6A initiators and have been proved to perform critical roles in various diseases, especially human malignant tumors." (PMID 35305660, 2022). "Therefore, in different types of same cancer, owing to the differences in the expression of different “Readers”, METTL3 or METTL14 can have opposite effects in the same cancer type." (PMID 36561529, 2022).
cancer (continued). "The exception is that METTL14 is predominantly cancer-inhibiting." (PMID 35804965, 2022). "Therefore, the role of METTL14 in different cancer types has different impacts in the cancer progress." (PMID 34476213, 2021). "METTL3 and METTL14 are highly expressed in gastrointestinal cancer tissues and, consistent with this finding, a subset of miRNAs exhibits high m6A levels in similar types of cancer." (PMID 33564819, 2021). "As the Wnt/β-Catenin pathway is a complex signaling cascade, the identification of novel genes in the Wnt/β-Catenin pathway, such as METTL3 and METTL14, might provide additional therapeutic opportunities in cancer treatment." (PMID 34315512, 2021). "METTL14 has different roles in different tumors and can be either a cancer promoter or suppressor." (PMID 34863142, 2021). "The network showed that METTL14 was targeted by multiple DMPs in most cancer types." (PMID 33718187, 2021). "However, overexpression of METTL3 and METTL14 has also been indicated to suppress cancer cell growth." (PMID 33611339, 2021). "Interestingly, opposite regulatory roles of METTL3 and METTL14 were observed in some cancers including HCC." (PMID 34046411, 2021). "The agonist of METTL14 also has broad clinical application prospects in the treatment of cancer." (PMID 34476213, 2021). "Moreover, as PTEN is a crucial target in the chemotherapy-resistance and cancer immunotherapy, the regulation between METTL14 in the role of chemotherapy-resistance and cancer immunotherapy in STAD should be further studied." (PMID 34476213, 2021). "METTL14 has been reported to be a tumor suppressor gene in many cancers." (PMID 34699322, 2021). "METTL14, an m6A Lmethyltransferase, was found deregulated in multiple cancer types." (PMID 34458141, 2021). "METTL3 and METTL14 expression have been reported to promote tumourigenesis in several cancer types." (PMID 33461542, 2021). "In addition, the results from IHC staining of 72 pairs of CRC samples and adjacent para-cancer tissue further validated that METTL14 expression was notably reduced in CRC tissue." (PMID 34916487, 2021). "The METTL14 expression was gradually decreased during cancer progression." (PMID 34916487, 2021). "Therefore, it is urgently needed to further clarify the characterization of METTL3 and METTL14 in cancers." (PMID 33159022, 2020). "It is unclear whether the methyltransferase-like 14 (METTL14) protein promotes or suppresses cancer growth." (PMID 33134390, 2020). "Finally, we also provided evidence for the large transcriptome levels of METTL3 and METTL14 as cancer driver genes." (PMID 32211315, 2020). "Therefore, it is limited to study the role of METTL3 and METTL14 in cancer only from the perspective of catalyzing m6A modification." (PMID 33159022, 2020). "In this study, we downloaded the expression profile and clinical information of 307 patients from The Cancer Genome Atlas database and 64 patients from the Gene Expression Omnibus (GEO) database, and univariate Cox analysis revealed that METTL14 was a prognostic m6A RNA methylation regulator." (PMID 31943856, 2020). "METTL3 and METTL14 are the most widely studied m6A regulatory genes in various cancers." (PMID 32547941, 2020). "Indeed, increasing m6A through knocking down adenosine demethylases (FTO and ALKBH5) or overexpressing adenosine methyltransferases (METTL3 and METTL14) suppressed the cancer cell proliferation." (PMID 29228737, 2017). "Belonging to the Class I methyltransferase family, METTL3 usually forms stable heterodimer complexes with METTL14 through its methyltransferase activity to mediate m6A methylation, regulates a variety of biological processes and plays several functional roles as an oncogene in cancers." (PMID 39163514, 2024). "Proper regulation of METTL3 and METTL14 may help restore m6A landmarks to halt cancer progression." (PMID 39006762, 2024). "However, there is little research on the regulation of METTL14 in cancer chemotherapy resistance." (PMID 36810285, 2023).